IGF1 (insulin like growth factor 1)
Diseases named in the same sentence as IGF1 in open-access papers (continued):
Sharing a sentence is not in itself a finding about the gene and the disease.
acne (continued). "Thus, the beneficial effects of these particular probiotics arise from the regulation of IGF-1/mTORC1 metabolism and the increased expression of anti-inflammatory cytokines and molecules that affect the microbiota–gut–skin axis, reducing the exacerbated inflammation found in acne." (PMID 35889147, 2022). "The major hormones like androgens, insulin, and insulin-like growth factor-1(IGF-1) are responsible for the occurrence and development of acne vulgaris." (PMID 34067630, 2021). "Moreover, various mechanisms of insulin-like growth factor (IGF)-1 may aid the emergence of acne, such as through increased androgen stimulation and the disinhibition of the forkhead box (Fox)O1 transcription factor, leading to further activation of the androgen receptor (AR)." (PMID 34829964, 2021). "Insulin, insulin-like growth factor-1 (IGF-1), and defective nuclear transcription factor forkhead box protein O1 (FOXO1) promote acne by stimulating sebaceous lipogenesis and androgen signaling." (PMID 30959761, 2019). "According to a recent clinical study, consumption of L. rhamnosus SP1 for 12-weeks led to decreased IGF-1 and increased FOXO1 gene expression that ultimately resulted in alleviation of acne manifestations in adult patients." (PMID 30959761, 2019). "In the general population, adults with acne are reported to have elevated levels of serum IGF-1, and IGF-1 levels correlate with acne severity." (PMID 31416218, 2019). "Thus, probiotics could improve acne by regulating the IGF-1 level." (PMID 31284694, 2019). "IGF-1/AKT/mTORC1 signalling also increases the anti-apoptotic regulator survivin, which is upregulated in the skin of acne patients." (PMID 28927457, 2017). "The expression pattern of the IGF-1/IGF1R system thus perfectly fits to the hyperproliferative cell layers of SGs and infundibular keratinocytes observed in acne patients." (PMID 28927457, 2017). "Moreover, another group has proposed a hypothesis for the diet-induced impact of insulin/IGF-1 signaling in acne, as both high glycemic load and dairy proteins increase the serum levels of insulin and IGF-1, important promoters of sebaceous glands and sebaceous lipogenesis." (PMID 22898209, 2012). "Consistent with previous studies, we observed an increase of IGF-1 and IGF-1r in rat acne models and a strong correlation between the concentration of IGF-1 and the severity of inflammation, and phage was able to reduce C. acnes-induced over-expression of IGF-1 by lysing C. acnes." (PMID 38197658, 2024). "A randomized controlled study showed that supplementation with the probiotic Lactobacillus can decrease the gene expression of insulin-like growth factor 1 (IGF1) by 32% and increase the gene expression of forkhead box protein O1 (FOXO1) by 65%, improving the appearance of adult acne." (PMID 37894244, 2023). "In fact, IGF-1 has been shown to induce SREBF1 expression and lipogenesis in SEB-1 sebocytes via the activation of the PI3K/AKT pathway, whereas a low glycemic diet, which decreases IGF-1 serum levels, reduces SREBF1 expression in the sebaceous glands (SGs) of acne patients." (PMID 37998335, 2023). "An enlightening fact is that patients with Laron syndrome who have growth hormone receptor (GHR) mutations have an IGF-1 deficiency, and if they are not treated with IGF-1 recombinant, they never develop acne." (PMID 35889022, 2022). "Insulin and IGF-1 activate the PI3K/Akt cascade, which upregulates the nuclear export of forehead box protein O1 (FoxO1), as a key component in the process of acne formation, antagonizing the expression of SREBP-1c and suppressing the transactivation of AR to inhibit lipogenesis." (PMID 34067630, 2021).
acne (continued). "Metformin activates AMPK, increases insulin sensitivity, decreases IGF-1 levels, lowers androgenic hormone levels from the adrenal glands and ovaries, improves ovarian and functional adrenal hyperandrogenism in PCOS, and prevents the development of acne." (PMID 33255783, 2020). "Untreated individuals with Laron syndrome, a primary growth hormone (GH) resistance disorder due to a genetic defect of GHR, exhibit diminished congenital IGF-1 serum levels, are of short stature and never develop acne 49,50." (PMID 23614736, 2013). "Furthermore, studies have demonstrated that individuals with acne who do not adhere to the Mediterranean diet exhibit significantly elevated levels of IGF‐1 compared with those who adhere to this dietary pattern." (PMID 40013532, 2025). "A negative impact on the management of acne has since been attributed to a Western diet high in saturated fats, highly processed carbohydrates, and dairy products, mainly due to its direct effects on IGF-1." (PMID 38672789, 2024). "Moreover, IGF-1 can promote the proliferation and differentiation of sebocytes and IL-1β production, increase sebum through sterol regulatory element-binding protein (SREBP) and interact with androgens to promote the development of acne." (PMID 38585341, 2024). "In addition, variations in genes such as IGF1 and TGFB are suggested to influence the production of lipids in sebocytes, and may contribute to acne development." (PMID 33849530, 2021). "As these inflammatory mediators are thought to increase the inflammatory state of acne and to aggravate the initial acne lesion, we investigated whether or not BV and melittin could inhibit pro-inflammatory cytokine production in the C. acnes-induced acne model and IGF-1-stimulated SZ95 cells." (PMID 35328573, 2022). "Indeed, acne is absent in populations consuming less insulinotropic palaeolithic diets that exclude grains, milk, and dairy products and exhibit much lower insulin/IGF-1 signalling." (PMID 25977937, 2015). "Notably, acne is absent in populations consuming less insulinotropic Palaeolithic diets 1,7, which exclude grains, milk and dairy products and exhibit much lower insulin/insulin-like growth factor (IGF-1) signalling (IIS) 4,7." (PMID 23614736, 2013).
myeloma (100 papers, 2004 to 2026). "Bcl-3 was induced in myeloma cell lines by interleukin (IL)-6, IL-21, IL-15, tumor necrosis factor-α and IGF-1, and its upregulation was associated with increased proliferation of the cells." (PMID 19191868, 2009). "Additionally, insulin-like growth factor 1 (IGF-1) has been implicated in MM pathogenesis with its role of stimulating mitogenesis, promoting myeloma cell survival and secreting vascular endothelial growth factor, which is essential for angiogenesis." (PMID 35454812, 2022). "Furthermore, FAK is activated by IGF-1-mediated association of integrin β1 with IGF-1R in multiple myeloma cells grown in culture." (PMID 31215459, 2019). "In MM, IGF-1 plays a critical role as a growth factor, produced by both myeloma cells and osteoclasts within the bone marrow microenvironment." (PMID 40565082, 2025). "In MM, IGF-1 is recognized as a key growth factor, synthesized by both myeloma cells and osteoclasts within the bone marrow microenvironment." (PMID 40565082, 2025). "The involvement of IGF-1 in myeloma bone disease remains inadequately understood, primarily due to the limited data available in the current literature." (PMID 40565082, 2025). "This paradox underscores the necessity for further research to elucidate the mechanisms by which IGF-1 influences bone remodeling in the context of myeloma." (PMID 40565082, 2025). "The increased autonomy of nMA-INA6 cells can be explained by the upregulation of IGF-1, being the major growth factor for myeloma cell lines." (PMID 38598843, 2024). "Myeloma cells, depending on auto- and paracrine growth and survival factors like insulin-like growth factor 1, profit from their release from the bone marrow environment and degraded bone matrix, constituting a vicious cycle." (PMID 39695697, 2024). "IGF-1 signaling promotes myeloma cell survival and progression, whereas inhibition of IGF-1 signaling promotes the pro-apoptotic effects of chemotherapeutic drugs in MM." (PMID 36508077, 2023). "The role of Rg3 with IGF-1 was previously studied and it was shown that Rg3 decreased the expression of IGF-1, causing a reduced cell proliferation in multiple myeloma and breast tumours." (PMID 34208799, 2021). "IGF-1 promotes growth and proliferation of myeloma cells via activation of the IGF-1 receptor in addition to IL-6." (PMID 33435539, 2021). "Interactions with stromal cells produce cytokines like IL-6, VEGF, and IGF-1 which activate the PI3K/AKT/mTOR pathway in multiple myeloma patients, initiating a signaling cascade which promotes resistance to chemotherapy and cancerous progression." (PMID 35127532, 2021). "These fibroblast-like cells interact with MM cells, leading to the secretion of anti-apoptotic and myeloma growth-promoting cytokines, such as interleukin-6 (Il-6), insulin-like growth factor-1(IGF-1), and stromal cell-derived factor-1 (SDF-1)." (PMID 33842343, 2021). "Studies have reported that some basal or constitutive activity of MAPK, Interleukin-6 (IL-6), insulin-like growth factor-1 (IGF-1) or other signaling pathways have been found in these myeloma cells, which can promot cell proliferation." (PMID 34579758, 2021). "IGF-1 induces protein synthesis, enhances endoplasmic reticulum (ER) stress in myeloma cells, and enhances the activity of proteasome inhibitors (PIs)." (PMID 33435539, 2021). "Insulin growth factor-1 (IGF-1) is well known to play a critical role in driving myeloma cell survival through activation of distinct downstream signalling pathways independent of the cytokine IL-6." (PMID 32228485, 2020). "The analysis of the whole transcriptome data revealed different expression levels of several genes, such as JAK1, JAK2, JAK3, RAF, IL6R, NCAM (CD56), WHSC1, MCL1, BCL2, and IGF1, which showed myeloma pathogenesis." (PMID 30079703, 2019). "Previous reports have found that IGF-1 increased the degradation of BimEL protein by activation of ERK1/2 pathway in multiple myeloma." (PMID 31661816, 2019).
myeloma (continued). "IGF-1 blocked Bim expression in multiple myeloma through epigenetic and posttranslational mechanisms." (PMID 31661816, 2019). "Bone marrow stromal cells also secrete insulin-like growth factor 1 (IGF1), which in myeloma cells induces NF-κB-dependent expression of anti-apoptotic genes." (PMID 29772694, 2018). "The actions of IGF-1 on myeloma cells appear to be synergistic with those of IL-6 although mechanisms independent of IL-6 also have been demonstrated." (PMID 30544512, 2018). "It retained its activity in the presence of the soluble cytokines IL-6 and IGF-1 and when plasma cells were co-cultured with BMSCs from myeloma patients." (PMID 28633670, 2017). "With regard to bortezomib resistance, our previous studies showed that this was mediated in part through an increase in Insulin-like growth factor 1 secretion by myeloma cells." (PMID 29371952, 2017). "In multiple myeloma, growth factor cytokines such as IGF-1 and IL-6 mediate a complex signaling network which stimulates the proliferation of MM cells." (PMID 29254208, 2017). "Aberrant activation of the IGF1/IGF1R axis has been associated with worse prognosis in many tumors, including breast, colorectal, laryngeal, myeloma, and prostate." (PMID 26884344, 2017). "A number of studies have shown that several proteins participate in the migration of myeloma cells, such as insulin-like growth factor-1 (IGF-1), stromal cell-derived factor-1α, wingless-ints (Wnt), and integrin β-7." (PMID 27683032, 2016). "Within the growth signalling network of the myeloma microenvironment, IL-6, IGF-1 and insulin play a prominent role." (PMID 25887188, 2015). "XIAP is highly expressed in myeloma cells and is induced by IL-6 and IGF-1-mediated activation of NF-κB/MAPK/PI3K pathways." (PMID 26009993, 2015). "IGF-1 suppresses Bim expression in multiple myeloma through several mechanisms including activation of the Akt pathway, inactivation of FoxO3, promotion of ERK-induced proteasomal degradation of BimEL and epigenetic regulation of the bim and foxO3a promoters." (PMID 26405162, 2015). "It is well known that NF-κB plays an important role in promoting growth, survival, and chemoresistance of myeloma cells in BM through the regulation of IL-6 and insulin-like growth factor 1 (IGF-1) expression." (PMID 26579531, 2015). "IGF-1 treatment of multiple myeloma cells led to reduced histone H3 tail Lys9 (H3K9) acetylation, and increased H3K9 dimethylation, which contributed to the silencing of the bim and foxO3 genes." (PMID 26405162, 2015). "The growth stimulatory effect of IGF1 and IL-6 on multiple myeloma cells was completely abrogated by NPV-BGT226." (PMID 26405162, 2015). "Various soluble factors have been identified in the signaling crosstalk between myeloma and stromal cells including IGF-1, IL6, DKK-1, RANKL and activin A." (PMID 25887188, 2015). "IGF-1 produced by plasma cells, as well as by the marrow microenvironment, is a critical mediator of a number of downstream effects that contribute to multiple myeloma pathobiology." (PMID 24252210, 2013). "In multiple myeloma, BMSCs up-regulate the secretion of several factors (IL-6, IGF-1, VEGF, FGF, SDF-1 and TNFα) as a result of their direct interaction with myeloma cells through integrins and soluble factors produced by myeloma cells." (PMID 24304929, 2013). "It was shown that bortezomib-resistant myeloma cell lines and clinical samples from bortezomib-refractory MM patients displayed an activated IGF-1/IGF-1R signaling pathway and a high level of IGF-1 cytokine which were associated with bortezomib resistance." (PMID 24327604, 2013). "The IGF-1 receptor has been found to be over-expressed in myeloma and this aberrant expression, as well as higher IGF-1 levels, have been related to disease progression, severity, and prognosis." (PMID 24252210, 2013).
myeloma (continued). "Our results confirm the wide-ranging effect of IGF-1 inhibition on myeloma cells, including blockage of the G1 to S phase, reduced PI3K signalling and altered equilibrium of pro- and anti-apoptotic proteins." (PMID 21799925, 2011). "The effects of IGF-1 treatment on CKS1B-shRNA-induced myeloma cell death and growth inhibition were evaluated." (PMID 20930946, 2010). "Insulin-like growth factor I (IGF-1) is a well-recognized myeloma cell survival factor activating the STAT3 signaling pathway." (PMID 20930946, 2010). "Notably, these cells exhibit an increased expression of IGF-1 receptors on their surface, suggesting a heightened sensitivity to IGF-1 signaling in the context of myeloma progression." (PMID 40565082, 2025). "Additionally, it has been reported that IGF-1-stimulated VEGF production is mediated by the ERK pathway in multiple myeloma cells." (PMID 38658734, 2024). "In contrast, IGF1 promotes glycolysis in neurons, multiple myeloma cells, and osteoblasts." (PMID 36369360, 2022). "Thus, interaction between IGF-1 and IGF-1R is associated with angiogenesis and survival of myeloma cells, and IGF-1R is considered a therapeutic target." (PMID 33435539, 2021). "With regard to carcinogenesis, FAIM family members have been reported to be upregulated in multiple myeloma, which could promote cancer cell proliferation by activating the IGF-1 and AKT signaling pathways." (PMID 34568020, 2021). "IGF-1 regulates anti-apoptotic protein B cell lymphoma 2 (BCL2) in myeloma." (PMID 33435539, 2021). "High levels of IGF-1R, and/or its activating ligands IGF-1 and IGF-2 have been associated with various types of human cancer (e.g. multiple myeloma, breast, prostate, colon, lung, pancreas, Ewing’s sarcoma) and also found to correlate with increased invasiveness and metastatic potential." (PMID 31215459, 2019). "Importantly, the anti-MM activity of PTC-209 was upheld in the presence of major myeloma growth factors (IGF-1 and IL-6) as well as in co-culture with BMSCs." (PMID 26935956, 2016). "Importantly, the anti-MM activity was upheld in the presence of stromal support or myeloma growth factors insulin-like growth factor 1 (IGF-1) and interleukin 6 (IL-6)." (PMID 26935956, 2016). "Furthermore, interleukin-6 (IL-6) and insulin-like growth factor-1 (IGF-1) induce telomerase activity in myeloma cell lines." (PMID 25822740, 2015). "Similarly, insulin-like growth factor 1 (IGF-1), which acts as a growth and survival factor in multiple myeloma (MM), downregulates Bim expression in these malignant cells." (PMID 26405162, 2015). "Whether eosinophils and megakaryocytes express other prominent myeloma growth factors such as insulin-like growth factor type 1 (IGF-1), needs to be elucidated." (PMID 25272036, 2014). "Other factors such as IGF-1 are also important for myeloma growth in vivo." (PMID 25272036, 2014). "Since insulin and IGF-1 are important myeloma growth factors there may exist a selective pressure in MM to upregulate genes that couple insulin/IGF-1 signaling to metabolic effectors that promote aerobic glycolysis." (PMID 24280290, 2013). "The combination of the anti IGF-1R antibody with AS602868 increased the cytotoxic effect in MM cell lines, suggesting that simultaneous targeting of IGF-1 signalling and the NF-κB pathway could be of therapeutic value in multiple myeloma." (PMID 21799925, 2011). "IGF-1 and IL-6 have been extensively described as paracrine myeloma growth factors." (PMID 20465808, 2010). "Moreover, in vivo induction of the IGF-1 receptor has been reported in the murine myeloma model 5T33MM, and this induction was necessary for biological effects of IGF-1 in these experiments." (PMID 19187270, 2009). "Such pausing in mammals has not been the subject of recent investigation, although the G2-to-M transition is known to be regulated by the growth factor IGF-1—for example, in mammalian uterine cells, oligodendrocyte progenitors, spermatogonial stem cells, and multiple myeloma cells." (PMID 26551561, 2015).